IGLC3 (immunoglobulin lambda constant 3 (Kern-Oz+ marker))
Description:
Constant region of immunoglobulin light chains. Immunoglobulins, also known as antibodies, are membrane-bound or secreted glycoproteins produced by B lymphocytes. In the recognition phase of humoral immunity, the membrane-bound immunoglobulins serve as receptors which, upon binding of a specific antigen, trigger the clonal expansion and differentiation of B lymphocytes into immunoglobulins-secreting plasma cells. Secreted immunoglobulins mediate the effector phase of humoral immunity, which results in the elimination of bound antigens. The antigen binding site is formed by the variable domain of one heavy chain, together with that of its associated light chain. Thus, each immunoglobulin has two antigen binding sites with remarkable affinity for a particular antigen. The variable domains are assembled by a process called V-(D)-J rearrangement and can then be subjected to somatic hypermutations which, after exposure to antigen and selection, allow affinity maturation for a particular antigen.
Synonyms: IGLC
Tractability: Antibody: its Gene Ontology location is reachable by antibodies, with high confidence; UniProt places it where antibodies can reach, with medium confidence.
Gene: Immunoglobulin constant (C) gene on chromosome 22 (22,906,342 to 22,906,803, forward strand). Ensembl gene ENSG00000211679.
Subcellular location: Secreted; Cell membrane
Pathways (Reactome):
Immune System: Antigen activates B Cell Receptor (BCR) leading to generation of second messengers; CD22 mediated BCR regulation; Classical antibody-mediated complement activation; FCERI mediated Ca+2 mobilization; FCERI mediated MAPK activation; FCERI mediated NF-kB activation; FCGR activation; Fc epsilon receptor (FCERI) signaling; Immunoregulatory interactions between a Lymphoid and a non-Lymphoid cell; Initial triggering of complement; Regulation of Complement cascade; Regulation of actin dynamics for phagocytic cup formation; Role of LAT2/NTAL/LAB on calcium mobilization; Role of phospholipids in phagocytosis
Disease: FCGR3A-mediated IL10 synthesis; FCGR3A-mediated phagocytosis; Potential therapeutics for SARS
Hemostasis: Cell surface interactions at the vascular wall
Vesicle-mediated transport: Scavenging of heme from plasma
Gene Ontology:
Molecular function: antigen binding
Biological process: adaptive immune response; B cell receptor signaling pathway; immunoglobulin mediated immune response
Cellular component: blood microparticle; extracellular exosome; extracellular region; IgA immunoglobulin complex; IgD immunoglobulin complex; IgE immunoglobulin complex; IgG immunoglobulin complex; IgM immunoglobulin complex; plasma membrane
Genetic constraint (gnomAD): Missense variants: 34 observed, 41.08 expected, observed/expected ratio (o/e) 0.83, 90% interval 0.63 to 1.1. Synonymous variants: 18 observed, 15.89 expected, observed/expected ratio (o/e) 1.13, 90% interval 0.78 to 1.66.
Homologues: Orthologues: chimpanzee IGLC3 (98% identical), mouse Iglc1 (72% identical), rabbit IGLL1 (70% identical), rat Iglc1 (66% identical), mouse Iglc4 (65% identical), mouse Iglc3 (63% identical), mouse Iglc2 (61% identical). Paralogues in human: IGLC2 (99% identical), IGLC1 (95% identical), IGLL5 (94% identical), IGLC7 (92% identical), IGLL1 (83% identical), IGKC (38% identical), IGHA2 (36% identical), IGHA1 (34% identical), IGHM (33% identical), IGHG1 (31% identical), IGHG2 (31% identical), IGHG3 (31% identical), and 65 more.
Diseases named in the same sentence as IGLC3 in open-access papers:
IGLC3 is named in the same sentence as 10 diseases in open-access papers, as found by Europe PMC text mining. Sharing a sentence is not in itself a finding about the gene and the disease. The quoted sentences say what the papers report.
COVID-19 (3 papers, 2023 to 2025). A disease caused by infection with severe acute respiratory syndrome coronavirus 2. "Patients with severe COVID-19 displayed increased B cell activation and upregulation of IGLC3, a marker of antibody processing." (PMID 41168347, 2025). "The HD-COVID-19 group tended to express IgL subtype IGLC2, whereas the HDs with vaccine group tended to express IGLC3, and no markedly increased immunoglobulins were found in the HDs without vaccine group." (PMID 36911681, 2023).
Myeloma (2 papers, 2022 to 2025). "Interestingly, we discovered that a subset of C0 IGLC3+ myeloma cells is associated with the MIF signaling pathway, indicating its significance in the signaling network of this subpopulation." (PMID 40406148, 2025). "We hypothesized that C0 IGLC3+ myeloma cells are closely linked to the progression of MM as a result of these findings." (PMID 40406148, 2025). "We investigated the differentiation trajectories of malignant plasma cells and identified four major myeloma subpopulations: C0 IGLC3+, C1 IGHA1+, C2 IGHG1+, and C3 IGHG4+ myeloma cells." (PMID 40406148, 2025). "We discovered coordinated contacts between C0 IGLC3+ myeloma cells and other cell types by using CellChat communication pattern analysis." (PMID 40406148, 2025). "We next looked at the APP signaling network, and the findings indicated that monocyte/macrophages, C3 IGHG4+ myeloma cells, and C0 IGLC3+ myeloma cells had substantial relationships with one another." (PMID 40406148, 2025). "Next, we further analyzed the regulatory activity of TOP5 TF of C0 IGLC3+ Myeloma cells, and we visualized the expression of KLF6, NR3C1, IRF7, YY1 and JUN in all cells and different tissue sources." (PMID 40406148, 2025). "In the centrality score, the C0 IGLC3+ Myeloma Cells mainly played the roles of Receiver, Influencer and Mediator." (PMID 40406148, 2025). "After revealing the signaling pathways of each cellular interaction, next, we conducted a study on the signaling pathways in the C0 IGLC3+ Myeloma Cell sand other cells." (PMID 40406148, 2025). "Our research specifically demonstrated how C0 IGLC3+ myeloma cells coordinate their interactions with different cell types." (PMID 40406148, 2025). "In summary, we determined that C0 IGLC3+ Myeloma cells are malignant tumor cells with high proliferation capacity and low differentiation level, which are important for MM." (PMID 40406148, 2025). "The analysis identified four distinct subpopulations of myeloma cells, with the C0 IGLC3+ myeloma cells representing the least differentiated and most proliferative subset." (PMID 40406148, 2025). "The results of network centrality scoring showed that C0 IGLC3+ Myeloma Cells played the roles of Sender, Receiver, Mediator, and Influencer roles, with the main role as Influencer." (PMID 40406148, 2025). "We analyzed the regulatory activity of TOP5 TFs in C0 IGLC3+ Myeloma cells and found that KLF6 was actively regulated in MM, and IRF7 and NR3C1 might be active in MM." (PMID 40406148, 2025). "In a previous analysis we found that C0 IGLC3+ Myeloma cells are naive tumor cell population in MM." (PMID 40406148, 2025). "The regulatory activities of the four myeloma cell subpopulations varied in different regulatory modules, with some degree of regulatory activity of C0 IGLC3+ Myeloma cells in the M1 and M4 regulatory modules, C0 IGLC3+ Myeloma cells and C1 IGHA1+ Myeloma cells in the M2 regulatory module." (PMID 40406148, 2025). "In C0 IGLC3+ myeloma cells, NR3C1 exhibited strong regulatory activity, indicating that it might be crucial for controlling cell division and proliferation in this subpopulation." (PMID 40406148, 2025). "Interestingly, LAC3 (Iglc3) was upregulated in extracellular vesicles derived from the BM of myeloma-bearing mice, compared with control extracellular vesicles, and is involved in complement activation." (PMID 36713534, 2022). "The results showed that KLF6, NR3C1, IRF7 and YY1 were all actively regulated in C0 IGLC3+ Myeloma Cells, C1 IGHA1+ Myeloma Cells, and JUN was actively regulated in C0 IGLC3+Myeloma Cells, C1 IGHA1+ Myeloma Cells and C3 IGHG4+ Myeloma Cells." (PMID 40406148, 2025). "The results showed that C0 IGLC3+ myeloma cells had the highest differentiation potential, indicating that C0 IGLC3+ myeloma cells had the strongest proliferation ability and were naive tumor cells, followed by C1 IGHA1+ myeloma cells, C2 IGHG1+ myeloma cells, and C3 IGHG4+ myeloma cells." (PMID 40406148, 2025).
tumor (8 papers, 2020 to 2026). "These insights suggested that the early-stage C0 IGLC3+ cells, with their high stemness, could be crucial for tumor initiation, while the later-stage C3 cells, enriched for oxidative stress regulation, might play a role in tumor progression and resistance to treatment." (PMID 40406148, 2025). "In RNAss database, tumor stemness was confirmed to be negatively correlated with the expressions of IGLC1 (r = -0.15, P = 0.01), IGLC2 (r = -0.16, P = 0.01), IGLC3 (r = -0.15, P = 0.01), and IGLC6 (r = -0.13, P = 0.03) respectively." (PMID 37784026, 2023). "Except for IGLC4, IGLC5, and IGLC7, 4 IGLC (IGLC1, IGLC2, IGLC3, and IGLC6) expressions were positively correlated with infiltration scores of 6 tumor-infiltrating immune cells (B cell, T cell CD4, T cell CD8, neutrophil, macrophage, and DC)." (PMID 37784026, 2023). "In DNAss database, we found that tumor stemness was negatively correlated with the expressions of IGLC1 (r = -0.14, P = 0.02), IGLC2 (r = -0.13, P = 0.02), IGLC3 (r = -0.13, P = 0.02), and IGLC7 (r = -0.14, P = 0.01) respectively in CESC tissues." (PMID 37784026, 2023). "Tumor stemness was negatively correlated with the expressions of 4 IGLCs (IGLC1, IGLC2, IGLC3, and IGLC7) respectively in CESC tissues." (PMID 37784026, 2023). "In addition, the lesion IgG + and mucosa IgA + spots exhibited divergent B-cell receptor V/C gene usage, with IGLC2, IGLC3, IGLV3-1, and IGKV4-1 all enriched in the tumor, suggesting a difference in the adaptive response between the two plasma cell types." (PMID 38110959, 2023). "Indeed, as examples, the high expressions of fibroblasts, myofibroblast markers (COL1A1, COL1A2), and B cell markers (IGLC3, IGHG3) were found in our LMD-isolated stroma samples and TCGA tumor samples, but not in our LMD-isolated tumor parts." (PMID 33916417, 2021).
cancer (3 papers, 2023 to 2025). A tumor composed of atypical neoplastic, often pleomorphic cells that invade other tissues. "Among other cancers, IGLC3 was identified as a novel prognostic biomarker for intestinal-type gastric cancer (IGC), and its expression level was closely correlated with the onset and progression of IGC." (PMID 40406148, 2025).
IGLC3 also shares sentences with these, for which no sentence is quoted: bladder cancer (1 paper); breast carcinoma (1); cervical adenocarcinoma (1); colorectal cancer (1); metastatic tumors (1); squamous cell carcinoma (1).